MYOZ2 (myozenin 2)
Description:
Myozenins may serve as intracellular binding proteins involved in linking Z line proteins such as alpha-actinin, gamma-filamin, TCAP/telethonin, LDB3/ZASP and localizing calcineurin signaling to the sarcomere. Plays an important role in the modulation of calcineurin signaling. May play a role in myofibrillogenesis.
Synonyms: C4orf5; CS-1; FATZ-2; CMH16
Tractability: No criterion of Open Targets' tractability assessment is met for any kind of drug.
Gene: Protein-coding gene on chromosome 4 (119,128,431 to 119,187,789, forward strand). Ensembl gene ENSG00000172399.
Subcellular location: Cytoplasm, myofibril, sarcomere, Z line
Subcellular location (Human Protein Atlas): Cytosol; Nucleoplasm
Gene Ontology:
Molecular function: protein binding; telethonin binding; actin binding; FATZ binding; protein phosphatase 2B binding
Biological process: negative regulation of calcineurin-NFAT signaling cascade; negative regulation of transcription by RNA polymerase II; sarcomere organization; skeletal muscle fiber adaptation; skeletal muscle tissue development
Cellular component: actin cytoskeleton; sarcomere; Z disc
Genetic constraint (gnomAD): Loss-of-function variants: 19 observed, 26.98 expected, observed/expected ratio (o/e) 0.7, 90% interval 0.49 to 1.03. The upper end of that interval is the gene's LOEUF score, 1.03, which puts it in group 4 of 6, group 1 being the genes least tolerant of losing a copy. Missense variants: 270 observed, 335.46 expected, observed/expected ratio (o/e) 0.8, 90% interval 0.73 to 0.89. Synonymous variants: 92 observed, 113.72 expected, observed/expected ratio (o/e) 0.81, 90% interval 0.68 to 0.96.
Gene-disease validity (ClinGen):
ClinGen rates the evidence that MYOZ2 causes each of these diseases.
hypertrophic cardiomyopathy (autosomal dominant): Disputed. A condition in which the myocardium is hypertrophied without an obvious cause.
Homologues: Orthologues: chimpanzee MYOZ2 (99% identical), dog MYOZ2 (94% identical), pig MYOZ2 (93% identical), rabbit MYOZ2 (91% identical), macaque MYOZ2 (90% identical), mouse Myoz2 (88% identical), guinea pig MYOZ2 (88% identical), rat Myoz2 (87% identical), tropical clawed frog myoz2 (62% identical), zebrafish myoz2b (49% identical), zebrafish myoz2a (46% identical). Paralogues in human: MYOZ1 (33% identical), MYOZ3 (33% identical).
Diseases named in the same sentence as MYOZ2 in open-access papers:
MYOZ2 is named in the same sentence as 22 diseases in open-access papers, as found by Europe PMC text mining. Sharing a sentence is not in itself a finding about the gene and the disease. The quoted sentences say what the papers report.
hypertrophic cardiomyopathy (12 papers, 2013 to 2024). "CRYAB modulates cardiomyocyte apoptosis in cardiac disorders, ANK2 regulates cardiac ion channels, and MYOZ2 mutations are linked to hypertrophic cardiomyopathy." (PMID 38559672, 2024). "Mutations in the Z-disc protein MYOZ2 can cause myofibrillar disarray and hypertrophic cardiomyopathy and gene expression of MYOZ2 was significantly decreased in resting MFM vs. control horses." (PMID 30289745, 2018). "MYOZ2 is a sarcomeric calcineurin-binding protein residing in the Z-disk that plays a crucial role in myofiber formation and human hypertrophic cardiomyopathy." (PMID 29698438, 2018). "Myozenin-2 is a calcineurin-binding protein and plays an important role in hypertrophic cardiomyopathy through its effect on calcineurin activity." (PMID 24795895, 2014). "Of these proteins, MYH7, TPM1 and MYOZ2 are known to be important in hypertrophic cardiomyopathy, and may play a similar role in HFpEF." (PMID 36093146, 2022). "In our dataset, MYOZ2 (myoz2a), TPM1 (tpm1) and TNNC1 (tnnc1a) have been identified which are previously reported to be linked with diverse forms of dilated and hypertrophic cardiomyopathy." (PMID 26815362, 2016). "In cardiac and skeletal muscle, the products of MYOZ2 and MYOZ3 genes appear to influence the expression of calcineurin, which plays an important role in hypertrophic cardiomyopathy and skeletal muscle fiber differentiation." (PMID 24367523, 2013).
cardiac hypertrophy (7 papers, 2017 to 2025). "Although the influence of MYOZ2 on cardiac hypertrophy has been studied in humans, few studies have been carried out on it in sheep." (PMID 30041440, 2018). "Current evidence suggests that overexpression of MyoZ2 can inhibit calcineurin-dependent signaling and result in overload-induced cardiac hypertrophy as well as arterial hypertension." (PMID 29698438, 2018).
cardiomyopathy (7 papers, 2013 to 2025). A disease of the heart muscle or myocardium proper. "Moreover, they highlighted the significance of mutations in myozenin 2 (MYOZ2) as calcineurin inhibitors, underscoring their contribution to the onset of cardiomyopathy." (PMID 37837495, 2024). "In addition, telethonin interacts with calsarcin-1 (also known as FATZ-2 or myozenin-2), a cardiomyopathy candidate gene known to affect hypertrophic signalling via modulation of calcineurin activity." (PMID 23065501, 2013). "Being a part of a macromolecular mechanosensory complex, it has been shown to play a role in cardiomyopathies via their interaction with genes such as MLP (muscle LIM protein), MYOZ2 (myozenin 2), ANKRD2 (ankyrin repeat domain 2), and sAnk1 (small muscle-specific ankyrin 1)." (PMID 31426609, 2019).
COVID-19 (1 paper, 2022). A disease caused by infection with severe acute respiratory syndrome coronavirus 2. "Myozenin 2 was identified through Least absolute shrinkage and selection operator regression Analysis, which was down-regulated in both COVID-19 and periodontitis." (PMID 36414950, 2022). "By bioinformatics analysis, MYOZ2 is predicted to correlate to the pathogenesis and immune infiltrating of COVID-19 and periodontitis." (PMID 36414950, 2022). "The expression values of MYOZ2 in COVID-19 and periodontitis are shown in scatter plot, and the expression of MYOZ2 in COVID-19 and periodontitis is lower than that in the normal samples." (PMID 36414950, 2022). "By bioinformatics analysis, Myozenin 2 is predicted to correlate to the pathogenesis and immune infiltrating of COVID-19 and periodontitis." (PMID 36414950, 2022). "It is found in our study that MYOZ2 is down-regulated in both periodontitis and COVID-19." (PMID 36414950, 2022). "The down-regulation of MYOZ2 might lead to the less infiltration of the mentioned immune cells in periodontitis and COVID-19 to further affect the immune response during the pathogenesis of the two diseases." (PMID 36414950, 2022). "However, there are no research about the function of MYOZ2 in periodontitis and COVID-19." (PMID 36414950, 2022).
muscular dystrophy (1 paper, 2011). Muscular dystrophy (MD) refers to a group of more than 30 genetic diseases characterized by progressive weakness and degeneration of the skeletal muscles that control movement. "ANKRD1 and MYOZ2 were found to be related to muscular dystrophy." (PMID 21637832, 2011).
persistent atrial fibrillation (1 paper, 2017). "This extended gene network contained a number of transcription factors (Tbx5, Hand2, Fhl2, and Gata4) and ion/calcium handling genes (Ank2, Cacna2d2, Scn5a, Kcnd2, Kcnj5, Myoz2, Casq2, Csrp3, and Gja3) of interest in the context of atrial fibrillation." (PMID 28720711, 2017).
neuromuscular disease (1 paper, 2020). "It was suggested that MYOZ2 knockout mice had neuromuscular disease." (PMID 32552672, 2020).
MYOZ2 also shares sentences with these, for which no sentence is quoted: cancer (3 papers); dilated cardiomyopathy (2); heart failure (2); tumor (2); Arrhythmia (1); arterial hypertension (1); Cachexia (1); chronic kidney disease (1); Danon disease (1); hypertrophy (1); idiopathic dilated cardiomyopathy (1); immune system disease (1); nephrotic syndrome (1); periodontitis (1); tuberculosis (1).